THADA (THADA armadillo repeat containing)
Diseases named in the same sentence as THADA in open-access papers (continued):
Sharing a sentence is not in itself a finding about the gene and the disease.
colorectal cancer (1 paper, 2024). A primary or metastatic malignant neoplasm that affects the colon or rectum. "THADA is highly expressed in human colorectal cancer, and functions as an indispensable regulator of programmed death-ligand 1 (PD-L1) maturation." (PMID 38561668, 2024).
energy metabolism disorders (1 paper, 2021). "THADA encodes a thyroid adenoma-related protein in the thyroid, pancreas, and other tissues, which is related to energy metabolism disorders." (PMID 34795691, 2021).
glaucoma (1 paper, 2024). Increased pressure in the eyeball due to obstruction of the outflow of aqueous humor. "According to a previous study, the THADA gene is related with IOP in glaucoma GWASs." (PMID 39457566, 2024).
Hernia (1 paper, 2022). "Evidence for shared susceptibility was further provided at nine loci including 2p21 (THADA), 3p14.3 (ERC2), 3p13 FOXP1, 4q34.1 (HAND-AS1), 5p15.33 (CEP72), 7p15.2 (LOC646588), 7q33 (CALD1) and 9q22.31 (BARX1) of which eight were previously discovered on individual hernia GWAS analyses." (PMID 36584111, 2022).
hyperlipidemia (1 paper, 2019). "Additionally, in T2D individuals, the levels of THADA tv5 correlated reversely with hyperlipidemia and those of IGF2BP2 tv7 positively with BMI (p < 0.05)." (PMID 30728419, 2019).
thyroid (1 paper, 2011). "The aim of this study was to analyze THADA expression in thyroid tissue in comparison to other tissues and to thyroid hyper- and neoplasias to elucidate the possible correlation of THADA mRNA with thyroid differentiation and neoplastic growth." (PMID 22050638, 2011). "The aim of this study was to quantify THADA gene expression in normal tissues and in thyroid hyper- and neoplasias, using real-time PCR." (PMID 22050638, 2011).
thyroid nodule (1 paper, 2023). A small circumscribed mass in the THYROID GLAND that can be of neoplastic growth or non-neoplastic abnormality. "This study confirms that further research assessing RET/PTC and THADA/IGF2BP3 rearrangements in suspicious thyroid nodules is necessary to improve patient management, particularly for deciding if a targeted therapy plan can be developed." (PMID 37444504, 2023).
cancer (8 papers, 2011 to 2026). A tumor composed of atypical neoplastic, often pleomorphic cells that invade other tissues. "Single-nucleotide polymorphisms (SNPs) related to various cancers have been detected in the THADA gene." (PMID 40483304, 2025). "Finding BRAF mutations or PPARG, NTRK1, NTRK3 and ALK fusions were strong predictors of a higher risk of cancer (approaching 100%) while other mutations like RAS, PTEN and EIF1AX or THADA fusions were associated with a significant but lower risk of cancer." (PMID 37510219, 2023). "Notably, THADA overexpression increases cancer growth and malignancy via augmenting the mechanistic target of rapamycin (mTOR) pathway or upregulating PD-L136–38." (PMID 40483304, 2025). "Three different inhibitors of Na+,K+-ATPase (cardiac glycosides such as ouabain, oleandrin, and digoxin) inhibited the proliferation of human cancer cells (KB and HepG2 cells), and markedly decreased the expression levels of THADA, LAT1, and 4F2hc in the cells." (PMID 38561668, 2024). "Interestingly, the knockdown of THADA inhibited cancer cell proliferation, and the proliferation was significantly rescued by re-expression of THADA in the THADA-knockdown cells." (PMID 38561668, 2024). "In the present study, we examined whether THADA contributes to the cardiac glycoside-induced anti-cancer mechanism and found that THADA is negatively regulated in the mechanism." (PMID 38561668, 2024). "Furthermore, the knockdown of THADA represses cancer growth." (PMID 40483304, 2025). "On the other hand, THADA may be involved in cancer pathogenesis." (PMID 38561668, 2024). "In future studies, it is necessary to clarify the mechanism of action of cardiac glycosides by using the THADA-, LAT1-, or 4F2hc-overexpressing cancer cells." (PMID 38561668, 2024). "Cardiac glycosides selectively inhibit α3NaK at nanomolar concentrations, suppressing cancer cell proliferation through GLUT1 endocytosis, metabolic inhibition, and downregulation of THADA and LAT1, ultimately inducing anoikis in CTCs and reducing metastasis in vivo." (PMID 41751935, 2026).
tumor (5 papers, 2008 to 2024). "In this study, GC patients in the GEO dataset GSE62254 were divided into two groups according to THADA expression (150 High vs 150 Low), and the augmentation of tumor-associated signaling pathways between the two groups was analyzed by using GSEA." (PMID 38234670, 2024). "Whereas the intact THADA may be involved in maintaining the differentiation of thyroid epithelium, the truncated allele might play a key role in tumor development of the thyroid." (PMID 22050638, 2011).
metabolic disorder (1 paper, 2020). "This genotype-phenotype study thus provides clues that THADA, INSR, TOX3, and DENND1A play a role in PCOS possibly through a metabolic disorder-related pathway." (PMID 32425888, 2020). "It suggests that THADA, INSR, TOX3, and DENND1A might play a role in PCOS through a metabolic disorder related pathway." (PMID 32425888, 2020).
reproductive diseases (1 paper, 2017). "The expression pattern at rs12478601 (THADA locus) in skin and fat, rs804279 (GATA4 locus) and rs1795379 (KRR1 locus) in fat and rs2268361 (FSHR locus) in skin predicted involvement in reproductive diseases." (PMID 28068351, 2017).
THADA also shares sentences with these, for which no sentence is quoted: Crohn disease (2 papers); dyslipidemia (2); prostate carcinoma (2); acute lymphoblastic leukemia (1); age-related hearing impairment (1); Allergy (1); anaplastic carcinomas (1); benign thyroid tumors (1); chronic myeloid leukemia (1); cleft lip (1); cleft palate (1); endometriosis (1); gestational diabetes (1); Glucose intolerance (1); Headache (1); inflammatory bowel disease (1); leukemia (1); papillary carcinoma (1).